TERF2 (telomeric repeat binding factor 2)
Diseases named in the same sentence as TERF2 in open-access papers:
TERF2 is named in the same sentence as 44 diseases in open-access papers, as found by Europe PMC text mining. Sharing a sentence is not in itself a finding about the gene and the disease. The quoted sentences say what the papers report.
breast cancer (7 papers, 2005 to 2025). A primary or metastatic malignant neoplasm involving the breast. "TERF2 IVS6+27G>A (E3673_301) was also associated with a reduced risk of breast cancer in individuals with a family history of breast cancer, however, the functional significance of the SNP is unknown." (PMID 17848914, 2007). "We established a score of expression for TERF2 inspired from HER2 evaluation in breast cancers (proportion of labeled cells and labeling intensity) to standardize TERF2 detection in OSCC." (PMID 27329590, 2016). "TERF2 has been found to be overexpressed in colorectal carcinoma, breast cancer, gastric cancer, glioblastoma, head and neck squamous cell carcinoma, hepatocellular carcinoma, acute myeloid leukemia, lung cancer, renal cell carcinoma, skin cancer and oral squamous cell carcinoma." (PMID 39328506, 2024). "Moreover, TERF2 mRNA expression is inversely related to survival in breast carcinoma (P = 0.045), colon carcinoma (Overall survival; P = 0.008; Disease free survival; P < 0.001) and prostate adenocarcinoma (Overall survival; P = 0.002)." (PMID 27329590, 2016). "In addition, women with a family history also showed a borderline statistically significant positive association between TERF2 IVS-42T>C variant alleles and breast cancer risk (OR 1.57, 96% CI 0.97–2.55, P interaction 0.06)." (PMID 17848914, 2007). "Telomeric repeat-binding factor 2 (TRF2) has been observed to be overexpressed in a variety of human cancers, including breast cancer, and has been demonstrated to promote cancer cell escape." (PMID 40831937, 2025). "Herein, hTERT was markedly downregulated and TERF2 markedly upregulated by Neratinib in AU565 cells, indicating an inducing effect of Neratinib on cell senescence in mammary cancer cells by impacting the telomerase activity." (PMID 38829772, 2024). "In a population-based study of 1995 breast cancer cases and 2296 controls from Poland, 24 SNPs representing common variation in POT1, TEP1, TERF1, TERF2 and TERT were genotyped." (PMID 17848914, 2007). "We studied CBFA2T3, FANCA, FBXL8, LRRC29, TERF2 and TERF2IP, six potential breast cancer TSG candidate genes located on the long arm of chromosome 16, which is involved in LOH in more than 50% of breast cancer cases." (PMID 16280054, 2005).
oral carcinoma (4 papers, 2016 to 2024). "TERF2 downregulates CXCL9 expression in oral carcinoma cell lines." (PMID 39328506, 2024). "TERF2 is a robust predictor of patient survival in cervical cancer and oral carcinoma." (PMID 33748108, 2021).
atherosclerosis (3 papers, 2021 to 2022). A disease characterized by the build-up of fatty material and calcium deposition in the arterial wall resulting in partial or complete occlusion of the arterial lumen. "It has been demonstrated that the loss of telomeric repeat-binding factor-2, which is crucial for maintaining telomeres, promotes plaque VSMC senescence and exacerbates plaque instability in atherosclerosis." (PMID 36082127, 2022). "We here investigate a role of EC senescence in atherosclerosis by utilizing EC-specific progeroid mice that overexpress the dominant negative form of telomeric repeat-binding factor 2 under the control of the Tie2 or vascular endothelial cadherin promoter." (PMID 34272458, 2021). "Disturbed blood flow induces the phosphorylation of telomeric repeat-binding factor 2 (TERF2)-interacting protein and subsequent nuclear export of its complexes with TERF2 in vitro and in vivo, instigating atherosclerosis." (PMID 34220553, 2021).
hepatocellular carcinoma (3 papers, 2019 to 2024). A malignant tumor that arises from hepatocytes. "Upregulation of TERF2 has been previously observed in hepatocellular carcinoma and cervical cancer where it has a positive impact on survival in patients with advanced stage cancer." (PMID 35054812, 2022). "Interestingly and consistently with our gene expression data, TERF2 and ARID1A, which are two of the most frequently altered genes in hepatocellular carcinoma (HCC), were among these peptides." (PMID 31783479, 2019).
acute myeloid leukemia (2 papers, 2024). Acute myeloid leukemia (AML) is a group of neoplasms arising from precursor cells committed to the myeloid cell-line differentiation. "TERF1, TERF2, TINF2, and POT1 are significantly expressed in testicular, Acute Myeloid Leukemia (AML), prostate and breast as well as renal cancers, respectively." (PMID 39578854, 2024).
colorectal cancer (2 papers, 2024). A primary or metastatic malignant neoplasm that affects the colon or rectum. "CTCF interacts with telomeric repeat binding factor 2 (TRF2) to promote the proliferation of colorectal cancer." (PMID 38436544, 2024).
glioblastoma (2 papers, 2024 to 2025). The most malignant astrocytic tumor (WHO grade IV). "Inhibition of TERF2 suppresses renal cell carcinoma cell proliferation and migration, while TERF2 depletion affects glioblastoma stem cell proliferation." (PMID 39328506, 2024). "miR-490* constrains proliferative capacity in glioblastoma by repressing telomere-maintenance genes Telomeric Repeat-binding Factor 2 (TERF2), Tankyrase 2 (TNKS2) and Serine/Threonine-protein kinase, (SMG1), inducing telomere dysfunction and DNA-damage signalling." (PMID 41468376, 2025).
glioma (2 papers, 2024 to 2025). A benign or malignant brain and spinal cord tumor that arises from glial cells (astrocytes, oligodendrocytes, ependymal cells). "Another notable identified glioma risk locus regarding leukocyte telomere length is PARP1, known not only for its role in DNA repair but also for its ability to regulate the binding of TRF2 (Telomeric repeat-binding factor 2), a shelterin subunit, to telomeric DNA." (PMID 38240992, 2024).
head and neck squamous cell carcinoma (2 papers, 2016 to 2024). A squamous cell carcinoma that arises from any of the following anatomic sites: lip and oral cavity, nasal cavity, paranasal sinuses, pharynx, larynx, and salivary glands. "Notably, TERF2 mRNA overexpression is inversely related to overall survival in head and neck squamous cell carcinoma, which strongly supports our results on an independent cohort of patients." (PMID 27329590, 2016).
leukaemia (2 papers, 2021 to 2024). "Histological examination revealed extensive infiltration of TERF2::PDGFRB‐positive leukaemia cells into various tissues, including bone, liver and spleen." (PMID 38323741, 2024). "Previous studies have identified various genes including EPOR, TCFL5, and TERF2 to be specifically overexpressed in ETV6-RUNX1 leukemia." (PMID 33708624, 2021). "Furthermore, targeted RNA sequencing (RNA‐seq) of leukaemia blast cells revealed the presence of a novel TERF2::PDGFRB fusion gene, involving an in‐frame fusion of exon 9–23 of PDGFRB with exon 1–8 of the TERF2 gene." (PMID 38323741, 2024). "Moreover, our experiments using BALB/c mice have shown that Ba/F3 cells carrying the TERF2::PDGFRB fusion gene are capable of inducing leukaemia in vivo and are notably sensitive to imatinib treatment." (PMID 38323741, 2024). "The TERF2::PDGFRB gene fusion resulted in fully penetrant leukaemia development." (PMID 38323741, 2024).
skin cancer (2 papers, 2024). "Shelterin expression predicted patient survival in 24 cancer types, with TERF1, TERF2, TINF2, and POT1 significantly expressed in testicular, AML, prostate, breast and renal cancers, respectively, and TPP1 in AML and skin cancer." (PMID 39578854, 2024).
Ataxia (1 paper, 2017). Ataxia refers to impaired coordination of voluntary muscle movement.
dysplastic nevi (1 paper, 2012). "The gene regions around RECQL4, RTEL1 and TERF2 were associated with melanoma, the presence of dysplastic nevi and number of nevi, respectively, in the Italian combined study." (PMID 23300679, 2012).
endothelial dysfunction (1 paper, 2023). In vascular diseases, endothelial dysfunction is a systemic pathological state of the endothelium (the inner lining of blood vessels) and can be broadly defined as an imbalance between vasodilating and vasoconstricting substances produced by (or acting on) the endothelium. "In addition, a decrease in the level of telomeric repeat-binding factor 2 (TRF2) in VSMCs derived from human plaques suggests the emergence of cell senescence and promotes endothelial dysfunction." (PMID 36744254, 2023).
esophageal cancer (1 paper, 2024). A primary or metastatic malignant neoplasm involving the esophagus. "Nonetheless, the expression, function, and diagnostic utility of TERF2 in esophageal cancer remain relatively understudied." (PMID 39328506, 2024). "This study aimed to quantify TERF2 expression levels, evaluate their diagnostic utility, explore their biological role, and examine the influence of TERF2 on cell proliferation in esophageal cancer." (PMID 39328506, 2024).
esophageal squamous cell carcinoma (1 paper, 2024). Esophageal squamous cell carcinoma (ESCC) is a type of esophageal carcinoma (EC) that can affect any part of the esophagus, but is usually located in the upper or middle third. "The expression levels of TERF2 were assessed in esophageal squamous cell carcinoma (ESCC) samples using RT-PCR, IHC, and Western blotting (WB)." (PMID 39328506, 2024).
lung adenocarcinoma (1 paper, 2016). A carcinoma that arises from the lung and is characterized by the presence of malignant glandular epithelial cells. "Alternately, TERF1 (an homologue of TERF2 present in the shelterin complex) and TERF2 expression levels were directly related to survival in lung adenocarcinoma (TERF2, disease free survival; P = 0.0097) and lung squamous cell carcinoma (TERF1, overall survival; P = 0.0065)." (PMID 27329590, 2016).
nevus (1 paper, 2012). Nevus (or naevus, plural nevi or naevi, from nævus, Latin for "birthmark") is the medical term for sharply circumscribed[1] and chronic lesions of the skin or mucosa. "The TERF2 region had the strongest association with nevus count (gene-based P-value = 0.009)." (PMID 23300679, 2012). "In the gene-based analysis, the TERF2 region had the strongest association with nevus count, suggesting that further research into this gene region and its role in nevi development may prove informative." (PMID 23300679, 2012).
oral squamous cell carcinoma (1 paper, 2024). "Additionally, TERF2 knockdown significantly reduces oral squamous cell carcinoma xenograft growth in mice, highlighting its potential as a therapeutic target." (PMID 39328506, 2024).
Parkinson disease (1 paper, 2019). A progressive degenerative disorder of the central nervous system characterized by loss of dopamine producing neurons in the substantia nigra and the presence of Lewy bodies in the substantia nigra and locus coeruleus. "The results also showed a number of genes that decreased in an Mn dose-dependent manner which include genes involved in iron transport (TF), protective activity of telomeres (TERF2), neurosensory function (MYO15a, OR1F1), and neurological disease such as ADHD (DIRAS2) and Parkinson’s disease (FRK)." (PMID 31396262, 2019).
pituitary adenoma (1 paper, 2024). "Serum TERF2 levels were measured in patients with pituitary adenoma (n = 40) and the reference group (n = 40)." (PMID 38339395, 2024). "TERF1 rs1545827, TNKS2 rs10509637 and rs10509639, TERF2 rs251796, ZNF676 rs412658, and CTC1 rs3027234 genes’ single nucleotide polymorphisms were analyzed to evaluate the associations with pituitary adenoma relapse." (PMID 38339395, 2024).
Sepsis (1 paper, 2025). Sepsis is defined as life-threatening organ dysfunction caused by a dysregulated host response to infection. "miR-29b-1-5p targetedly inhibits TERF2, thereby enhancing sepsis-induced myocardial injury." (PMID 40041174, 2025).
cancer (15 papers, 2012 to 2025). A tumor composed of atypical neoplastic, often pleomorphic cells that invade other tissues. "Activation of the Wnt/β-catenin signaling pathway upregulates TERF2 expression, a critical mechanism underlying aberrant cancer cell growth." (PMID 39328506, 2024). "Upregulated TERF2 expression was significantly associated with cancer stages 1–4, tumor grades 1–3, and lymph node metastasis statuses N0, N2, N3, and N4." (PMID 39328506, 2024). "First, TMS causes telomere dysfunction, which is associated with dissociation of telomeric repeat-binding factor 2 (TRF2) from telomeres in cancer cells." (PMID 28620243, 2017). "Paradoxically, cancer cells (CCs) require adequate shelterin to sustain their rapid proliferation, and increased levels of shelterin proteins such as TERF1, TERF2, and TINF2 are associated with tumour development." (PMID 39578854, 2024). "ESCA samples exhibited significantly increased TERF2 mRNA levels compared to non-carcinoma controls, a finding independently validated by TCGA database analysis." (PMID 39328506, 2024). "The Telomeric Repeat binding Factor 2 (TRF2) regulated by the Wnt/β-catenin pathway is overexpressed in several human cancer where its promote tumor immune escape and angiogenesis favoring tumor growth and metastasis." (PMID 36189271, 2022). "TERF2 is over-expressed in many cancers but its correlation to patient outcome remains controversial in OSCC." (PMID 27329590, 2016). "Over-expression of TERF2 is observed in a variety of human cancers, suggesting that TERF2 plays a key role in tumor initiation and development." (PMID 27329590, 2016). "Recently, increasing evidence suggests that telomere maintenance genes, such as TERT, TERC, TERF1, TERF2, TINF2, TERF2IP and POT1 are associated with cancer risk." (PMID 22970196, 2012). "IHC analysis revealed pronounced TERF2 overexpression in cancer tissues." (PMID 39328506, 2024). "Furthermore, TERF2 overexpression correlates with patient sex, tumor grade, cancer stage, LNM, and tumor histology." (PMID 39328506, 2024). "Changes in several shelterin components, such as TERF2, TERF1, and TINF2, have been identified in human cancers, highlighting potential therapeutic targets to combat cellular ageing and telomerase activity in various cancers." (PMID 39578854, 2024). "TERF2 protein and mRNA expression were elevated in ESCC tissues and correlated with age, sex, cancer stage, tumor grade, lymph node metastasis (LNM), and tumor histology." (PMID 39328506, 2024). "Telomeric repeat-binding factor 2 (TRF2), a known cancer advancement contributor, regulates telomere maintenance and has been identified to be downregulated by miR-182-3p in TNBC." (PMID 38002007, 2023). "We found telomere maintaining genes (TERF2, CTC1, and ACD), genes involved in zinc homeostasis (MTF1 and SLC30A9), transcription elongation factor complex components (ICE1, ICE2, ELL), and BCL6 corepressors (BCOR, BCORL1) uniquely invoked in TNBC cancers." (PMID 40700427, 2025).
tumor (10 papers, 2005 to 2025). "Sections from tumors generated with control or knock-down cells for TERF2 were analyzed to understand the mechanism associated with reduced tumor growth." (PMID 27329590, 2016). "Notably, NK cell activation has previously been associated to a decrease in TERF2 tumor expression." (PMID 27329590, 2016). "TERF2-dependent tumor aggressiveness was tested by generating tumors in nude mice with CAL33 expressing the luciferase gene (CAL33-Luc cells) and control or two independent TERF2-directed shRNA sequences." (PMID 27329590, 2016). "Furthermore, TERF2 mRNA levels correlate with serum levels of the tumor markers CEA, CYFRA21-1, and TPA." (PMID 39328506, 2024). "Additionally, increased TERF2 mRNA levels correlated with tumor histology, age, and sex compared to normal tissues." (PMID 39328506, 2024). "Emerging evidence indicates that TERF2 interacts with multiple tumor-related pathways." (PMID 39328506, 2024). "Furthermore, previous studies have demonstrated TERF2's role in modulating proliferation in various tumor types." (PMID 39328506, 2024). "Previous reports have implied abnormally high or low expression of TERF2 may lead to chromosomal instability and induce fatal tumour changes." (PMID 35054812, 2022). "We assessed whether the Telomeric Repeat-binding Factor 2 (TERF2) influences tumor aggressiveness and treatment response." (PMID 27329590, 2016). "Instead, TERF2 may influence the expression of factors that act on cells of the tumor microenvironment." (PMID 27329590, 2016). "Furthermore, we examined the relationship between TERF2 mRNA levels and serum tumor markers." (PMID 39328506, 2024). "TERF2 has remarkable tumor-specific effects; however, its role in PDAC remains unknown." (PMID 33748108, 2021). "However, the link between TERF2 expression in tumor tissues, overall survival and treatment response remains unclear." (PMID 27329590, 2016). "Therefore, high expression of TERF2 in tumors may repress of a panel of cytokines that enhance an anti-tumor immune response." (PMID 27329590, 2016). "In this study, we systematically assessed the prognostic performance of DNA replication-related genes for predicting tumor recurrence and constructed a novel and robust signature including EREG, KCTD13, MCM3AP, MCM3, POLD2, TERF2, and TP73." (PMID 33748108, 2021). "Western blot analysis of 39 paired ESCC samples demonstrated 27 tumor tissues significantly higher TERF2 protein levels than non-tumor controls." (PMID 39328506, 2024). "A multivariate analysis showed that the TERF2 score (OR = 2.35 [1.01 – 5.45] 95% CI, P = 0.0424) was independent of tumor size (OR = 3.45 [1.387 – 8.628] 95% CI, P = 0.007) introducing a new biological prognostic marker of survival for OSCC." (PMID 27329590, 2016). "Our results illustrate that overexpression of TERF2 in OSCC is a predictor of poor prognosis independent of tumor size." (PMID 27329590, 2016). "The implication of TERF2 in angiogenic processes has been described recently through direct regulation of the platelet-derived growth factor receptor β in endothelial cells, but not directly in the tumor cells." (PMID 27329590, 2016). "TERF2-dependent survival time was independent of tumor size in a multivariate analysis." (PMID 27329590, 2016). "Possible candidates CBFA2T3, TERF2 and TERF2IP, FBXL8 and LRRC29 and FANCA were studied for insertion and deletion mutations and for expression differences using quantitative RT-PCR in a panel of tumour cell lines and primary tumours with and without loss of 16q." (PMID 16280054, 2005). "Two genes involved in telomere maintenance, TERF2 and TERF2IP were among those ruled out as tumor suppressors on 16q, as was E2F4." (PMID 16620391, 2006).
TERF2 also shares sentences with these, for which no sentence is quoted: cervical cancer (2 papers); age-related macular degeneration (1); colon carcinoma (1); diabetes mellitus (1); gastric cancer (1); lung carcinoma (1); lung squamous cell carcinoma (1); melanoma (1); neuroblastoma (1); neurodevelopmental disorder (1); neurological disease (1); non-small cell lung carcinoma (1); Obesity (1); osteoporosis (1); prostate adenocarcinoma (1); prostate carcinoma (1); renal carcinoma (1); renal cell carcinoma (1); short telomere syndrome (1); thyroid cancer (1).